ZP2 (zona pellucida glycoprotein 2)
Description:
Component of the zona pellucida, an extracellular matrix surrounding oocytes which mediates sperm binding, induction of the acrosome reaction and prevents post-fertilization polyspermy. The zona pellucida is composed of 3 to 4 glycoproteins, ZP1, ZP2, ZP3, and ZP4. ZP2 may act as a secondary sperm receptor.
Synonyms: Zp-2; ZPA; OOMD6; OZEMA6
Tractability: Antibody: its Gene Ontology location is reachable by antibodies, with high confidence; UniProt places it where antibodies can reach, with medium confidence; UniProt predicts a signal peptide or a membrane-spanning region.
Gene: Protein-coding gene on chromosome 16 (21,197,450 to 21,214,510, reverse strand). Ensembl gene ENSG00000103310.
Subcellular location: Zona pellucida (Processed zona pellucida sperm-binding protein 2); Cell membrane
Pathways (Reactome):
Developmental Biology: M-decay: degradation of maternal mRNAs by maternally stored factors
Reproduction: Interaction With Cumulus Cells And The Zona Pellucida
Gene Ontology:
Molecular function: acrosin binding; identical protein binding; protein binding; structural constituent of egg coat; coreceptor activity
Biological process: regulation of acrosome reaction; binding of sperm to zona pellucida; prevention of polyspermy
Cellular component: egg coat; endoplasmic reticulum; extracellular matrix; extracellular region; multivesicular body; plasma membrane
Genetic constraint (gnomAD): Loss-of-function variants: 51 observed, 87.45 expected, observed/expected ratio (o/e) 0.58, 90% interval 0.47 to 0.74. The upper end of that interval is the gene's LOEUF score, 0.74, which puts it in group 3 of 6, group 1 being the genes least tolerant of losing a copy. Missense variants: 905 observed, 953.41 expected, observed/expected ratio (o/e) 0.95, 90% interval 0.9 to 1. Synonymous variants: 373 observed, 347.27 expected, observed/expected ratio (o/e) 1.07, 90% interval 0.99 to 1.17.
Homologues: Orthologues: chimpanzee ZP2 (99% identical), macaque ZP2 (94% identical), rabbit ZP2 (68% identical), dog ZP2 (67% identical), guinea pig ZP2 (65% identical), pig ZP2 (63% identical), mouse Zp2 (57% identical), rat Zp2 (56% identical), tropical clawed frog zp2 (35% identical), zebrafish zpax4 (13% identical). Paralogues in human: ZP4 (21% identical), ZP1 (18% identical), QRICH2 (10% identical), C16orf96 (9% identical).
Diseases named in the same sentence as ZP2 in open-access papers:
ZP2 is named in the same sentence as 14 diseases in open-access papers, as found by Europe PMC text mining. Sharing a sentence is not in itself a finding about the gene and the disease. The quoted sentences say what the papers report.
Infertility (13 papers, 2020 to 2025). "Nevertheless, several of these published mutations in ZP2—particularly the ones in the C-terminal region—are associated with infertility and implantation failure." (PMID 40697826, 2025). "Two homozygous truncating pathogenic variants of the ZP2 gene were identified using Sanger sequencing in infertile women with IVF fertilization failure." (PMID 36589837, 2022). "Twenty primary infertile women with ZP2 mutations were reported in pieces of literature, aged from 25 to 38 years old, with a history of infertility of 3 to 13 years." (PMID 36476320, 2022). "ZP2 is an important constituent of the zona matrix as ZP2 null female mice produce zona deficient oocytes and are infertile." (PMID 34869353, 2021). "In many cases, the proteinencoded by ZP2 is responsible for the integrity of the ZP structure and possiblemutations in the genes that can cause a defect in oocyte maturation and result incases of infertility." (PMID 35916458, 2023). "Knockout of Zp2 or Zp3 disrupts zona matrix assembly and folliculogenesis, leading to complete infertility in mice." (PMID 41394961, 2025). "A study identified two homozygous pathogenic variants (c.1695-2A > G and c.1691_1694 dup, respectively) of ZP2 in infertile patients from two different consanguineous families: both resulted in a thin ZP and IVF failure." (PMID 35140748, 2022). "Further, analyses of mutations in the gene encoding human zona proteins from infertile women suggest that ZP1, ZP2, and ZP3 have a role in fertility and assembly of ZP matrix." (PMID 33681199, 2021). "Notably, mouse models with impaired furin cleavage of ZP2 displayed infertility related to EFS phenotypes." (PMID 41394961, 2025). "In this study, we identified a homozygous nonsense mutation in ZP2 (c.1924C>T, p.Arg642X) in an infertile woman with a thin or no ZP phenotype and total fertilization failure in routine IVF, which could be fertilized by ICSI." (PMID 37293489, 2023). "Consequently, in the absence of fetuin-B, ZP2 cleavage occurs prematurely and leads to infertility of female fetuin-B deficient mice." (PMID 34320465, 2021). "For example, female mice lacking ZP2 or ZP3 failed to assemble ZP during oocyte growth, which in turn triggered oocyte and ovulation loss, thereby leading to infertility." (PMID 35813655, 2022). "ZP2-null or ZP3-null mice produced eggs without a ZP, as well as infertility." (PMID 36476320, 2022).
female infertility (7 papers, 2020 to 2025). Diminished or absent ability of a female to achieve conception. "ASTL is an ovastacin enzyme that is responsible for cleaving ZP2 to prevent polyspermy and has been linked to female infertility." (PMID 40073759, 2025). "Thus, inhibition of furin‐mediated cleavage of ZP proteins contributes to female infertility, with loss of ZP2 furin cleavage being specifically responsible for the occurrence of EFS." (PMID 41394961, 2025). "In the literature, ZP1, ZP2, and ZP3 gene alterations have been associated with female infertility, mainly on the grounds of ZP defects." (PMID 34501995, 2021). "Here, using mouse models with disrupted furin cleavage sites in ZP1, ZP2, and ZP3, we found that loss of the furin site in ZP2 caused female infertility associated with empty follicle syndrome (EFS), manifested by the failure to retrieve oocytes after ovarian hyperstimulation." (PMID 41394961, 2025). "Studies have reported that the variants in ZP1(MIM: 195000), ZP2 (MIM: 182888), and ZP3 (MIM: 182889) affect the formation of zona pellucida and result in female infertility, but there is no convincing evidence to prove that ZP4 (MIM: 613514) variant responsible for female infertility." (PMID 37052235, 2023). "Notably, impairment of furin cleavage in ZP2 causes female infertility associated with EFS in a dominant inheritance pattern, which is distinct from the previously reported thin‐ZP or free‐ZP oocytes resulting from biallelic loss‐of‐function mutations of Zp2 under a recessive inheritance pattern." (PMID 41394961, 2025). "Together, these findings suggested that disruption of furin‐mediated cleavage of ZP2 impairs ZP formation and perturbs the proper localization of ZP1 and ZP3, ultimately leading to female infertility consistent with EFS." (PMID 41394961, 2025). "Previous studies have reported that mutations in human ZP1, ZP2 and ZP3 influence their functions and result in a lack of ZP or in an abnormal oocytes and empty follicle syndrome, which leads to female infertility." (PMID 32573113, 2020).
empty follicle syndrome (4 papers, 2020 to 2025). "Mutations in ZP2 have been reported to cause ZP defects or empty follicle syndrome." (PMID 37293489, 2023). "Moreover, mutations in ZP1, ZP2, and ZP3 genes have been associated with empty follicle syndrome (EFS), marked by the absence of oocytes within follicles, highlighting the essential roles of ZP proteins not only in fertilization but also in folliculogenesis." (PMID 41394961, 2025).
colon carcinoma (2 papers, 2021 to 2022). "For that purpose, various tumor cell lines and more than 60 tissue samples from colon cancer patients were examined to analyze the potential of ZP2 as a putative diagnostic tumor marker." (PMID 33917056, 2021). "A recently published study describes the use of ZP2, a prominent protein of human oocyte zona pellucida, as a new colon cancer biomarker." (PMID 35330493, 2022). "Recently, ZP2 has been extensively studied in colon cancer evaluating its potential function and usability as new biomarker." (PMID 35330493, 2022). "Another gene of interest, namely ZP2, has recently been identified as new target molecule in colon cancer." (PMID 35330493, 2022). "The relatively high level of ZP2 mRNA in colon carcinoma cells prompted us to analyze ZP2 expression in primary colon cancer tissues." (PMID 33917056, 2021). "We have chosen ZP2 for further investigations regarding its potential as a new target molecule in colon cancer diagnosis/treatment." (PMID 33917056, 2021). "Since ZP2 shows an enhanced transcript level in colon cancer tissue, it seemed obvious to investigate its potential function in proliferative cellular processes." (PMID 33917056, 2021). "Its character as a membrane protein makes ZP2 even a potential target molecule for tumor therapy, especially as it positively affects colon cancer cell proliferation." (PMID 33917056, 2021). "According to our data, we propose that in colon tumor cells, ZP2 is expressed as a plasma membrane protein that, thereby, is capable as an upstream receptor and regulator of driving EXOSC5-ERK1/2-cyclinD1-signaling." (PMID 33917056, 2021). "Since ZP2 shows an enhanced transcript level in colon cancer cells, siRNA experiments have been performed to verify the potential role of ZP2 in cell proliferation." (PMID 33917056, 2021). "Our study shows ZP2 to be a new biomarker for diagnosis, best used in combination with other low abundant genes in colon cancer." (PMID 33917056, 2021). "In summary, our study shows ZP2 to be a new biomarker for diagnosis, best used in combination with other low abundant tumor marker genes in colon cancer." (PMID 33917056, 2021). "After having explored that ZP2 exhibits an enhanced mRNA level in colon cancer cells, the next step was to investigate its putative function in cell proliferation." (PMID 33917056, 2021). "We demonstrate that ZP2 mRNA is expressed in a low-abundant manner with high specificity in subsets of cancer cell lines representing different cancer subtypes and also in a significant proportion of primary colon cancers." (PMID 33917056, 2021). "Hence, the colon tumor cell line with the highest ZP2 expression rate, namely HT29, has been chosen for studying ZP2 effects on proliferation." (PMID 33917056, 2021). "Since ZP2 shows an enhanced transcript level in colon cancer cells, siRNA experiments have been performed to investigate whether down-regulation of ZP2 would affect cell proliferation." (PMID 33917056, 2021). "Based on these data, ZP2 might serve as a new target molecule for cancer diagnosis and treatment in respective cancer types such as colon cancer." (PMID 33917056, 2021). "A similar approach could also be useful in respect to colon cancer with antibodies against ZP2." (PMID 33917056, 2021). "Irrespective of these considerations, a higher ZP2 expression was measured in colon carcinoma cell lines." (PMID 33917056, 2021). "In order to investigate whether ZP2, Ki67, podoplanin, and EXOSC5 share the same tissue distribution, immunohistological analysis of colon cancer specimens has been performed." (PMID 33917056, 2021). "A 75% probability of ZP2 expression (three out of four experiments) was present in colon carcinoma COLO 320HSR and SW-480 cells, a 50% probability (two out of four experiments) took place in colon carcinoma SW-948 and U251 glioma cells, and a 25% probability was present for twelve cell lines (43%)." (PMID 33917056, 2021).
prostate carcinoma (2 papers, 2021 to 2022). A carcinoma that arises from epithelial cells of the prostate gland. "In addition, ZP2 protein has also been found in prostate cancer and corresponding PC3 cells, too, whereas ZP2 mRNA could, however, not be detected." (PMID 35330493, 2022). "Inter alia, Costa and colleagues have demonstrated that ZP1, ZP3, and ZP2, but not ZP2-specific transcripts, are expressed in prostate cancer-derived PC3 cells and prostate tumor tissue." (PMID 33917056, 2021).
breast carcinoma (1 paper, 2018). "Furthermore, DCT and ZP2 are high-profile biomarkers, and their role in breast cancer requires further investigation." (PMID 29589558, 2018). "For instance, PHTF1, MUC5AC, ZNF192, PCSK6, and HDGFRP3 are shown to be involved in breast cancer, and some common genes such as DCT, ZP2, and CEACAM7 might be involved in breast cancer." (PMID 29589558, 2018).
ovarian diseases (1 paper, 2023). "Some DEGs in F1 ovaries are related to reproductive/ovarian diseases, particularly POI (as Wt1, Bmpr2, Zp1, Zp2) and PCOS (as Tcf21, Fst, Bmpr2)." (PMID 36982971, 2023).
serous papillary adenocarcinoma (1 paper, 2011). "We report the presence of SSEA-4, SOX-2, VASA and ZP2-positive primitive oocyte-like cells in the adult ovarian surface epithelium of a patient with serous papillary adenocarcinoma." (PMID 21827672, 2011).
cancer (3 papers, 2018 to 2022). A tumor composed of atypical neoplastic, often pleomorphic cells that invade other tissues. "We would like to suggest that the expression pattern of genes such as ZP2 in cancer is linked to a general (epi)genetic instability inherent to such malignancies that inter alia leads to an increased “background noise” of low-abundant gene expression." (PMID 33917056, 2021). "In our study, we have basically concentrated on the potential of ZP2 expression as a biomarker tool for risk estimation in cancer diagnosis." (PMID 33917056, 2021). "In the present study, we have analyzed the potentials and limitations of low abundant-expressed molecules, i.e., ZP2, as cancer biomarkers." (PMID 33917056, 2021). "In future, it seems warranted to search for potential ligands of membrane-bound ZP2 that interfere with cancer-related processes, such as the cell cycle and signaling cascades." (PMID 33917056, 2021). "SAS1B has been shown to be exocytosed from oocyte cortical granules after fertilization to aid in the block to polyspermy by cleaving zona pellucida protein 2 (ZP2) surrounding two-cell embryos but it is unknown whether SAS1Bpos cancer cells secrete SAS1B." (PMID 29507667, 2018). "In our present study, ZP2 shows a specificity and sensitivity below 100% which excludes this gene as potential cancer-specific marker." (PMID 35330493, 2022). "Thus, the expression pattern of ZP2 in tumor cells may provide an opportunity for the detection of circulating or disseminated tumor cells in body fluids, and, in principle, for an early diagnosis of cancer via a negative selection mode strategy." (PMID 33917056, 2021).
tumor (2 papers, 2021 to 2022). "Recent studies with tumor cell lines showed ZP2 expression in few cell lines, whereas ZP3 has been found in various different tumors." (PMID 33917056, 2021). "Our study shows for the first time the expression of the zona pellucida glycoprotein ZP2 in various tumor cell lines as well as in tissue samples of healthy and cancerous colon." (PMID 33917056, 2021). "This study also shows ZP2 presence in cell culture of various tumor origin." (PMID 35330493, 2022). "In addition, a more detailed differential analysis focusing on different tumor stages revealed a significantly higher ZP2 expression rate in T2 and T3 tumor stages." (PMID 33917056, 2021). "Furthermore, the fact that ZP2 is located in the plasma/cytoplasmic membrane makes it a potential target molecule for tumor therapy." (PMID 33917056, 2021).
ZP2 also shares sentences with these, for which no sentence is quoted: glioma (1 paper); male infertile (1); prostate tumor (1); reproductive diseases (1).